CXCL12 (C-X-C motif chemokine ligand 12)
Diseases named in the same sentence as CXCL12 in open-access papers (continued):
Sharing a sentence is not in itself a finding about the gene and the disease.
cancer (continued). "Recent evidence verified that CXCL14 binds to CXCR4 and shows a synergistic effect with CXCL12 in cancers." (PMID 35452413, 2022). "Angiogenesis plays a critical role in normal development and the progression of cancer and is closely related to the CXCL12/CXCR4 axis." (PMID 35893797, 2022). "As is reported, CXCR4 is highly expressed in breast cancers, with the ligand CXCL12 showing the highest levels of expression in the organ where cancer metastases first occur." (PMID 35630915, 2022). "Metabolism reprogramming represents another hallmark of cancer, but few studies have investigated the potential effects of CXCL12 signaling through CXCR4 or ACKR3 on metabolic shifts in cancer cells." (PMID 35681470, 2022). "Analogously, extensive studies regarding the role of TA-MSCs in building cancer-associated vasculature largely concentrate on pro-angiogenic chemokines or growth factors such as VEGF, IL-6, and the CXCL12/CXCR4 axis." (PMID 36324128, 2022). "On the other hand, cancer cells can secrete neurotrophic growth factors or chemokines, such as CCL2 and CXCL12, to promote development of neural progenitors, causing nerve growth." (PMID 36612083, 2022). "CXCL12 levels were elevated in the plasma membrane of LARC cancer cells after nCRT and positive expression of CXCL12 in the plasma membrane of LARC cells after nCRT was correlated with a shorter FFR period." (PMID 34976180, 2022). "CXCR7 and CXCR4 are G protein-coupled receptors (GPCRs) that can be stimulated by CXCL12 in various human cancers." (PMID 36077241, 2022). "It has been verified that many natural products can produce anti-cancer and anti-viral effects through the CXCL12/CXCR4 axis, including flavonoids, isoflavones, bioketones, and isoprenoidyl flavonoids." (PMID 35893797, 2022). "Understanding pro-tumorigenic phenotype of MSCs and mechanisms of adhesion and heterocellular communication favoring their interaction with cancer PCs, will allow to manipulate critical pathways, including CXCL12/CXCR4 axis, thus improving disease outcome." (PMID 35064098, 2022). "CXCL12 is also known as stromal cell-derived factor 1 (SDF1), a crucial regulator in cancer initiation, angiogenesis, and metastasis." (PMID 35300411, 2022). "Chemokine receptors 7 (CXCR7) and 4 (CXCR4) are G protein-coupled receptors (GPCRs) that can be stimulated by a ligand, CXCL12, in various human cancers." (PMID 36077241, 2022). "C-x-C motif chemokine ligand 12 (CXCL12) is a crucial cancer immunity and angiogenesis regulator that triggers HCC progression through Wnt/β-catenin pathway regulation." (PMID 36118880, 2022). "The specificity of the anti-CXCL12 antibody was demonstrated by the capacity of recombinant CXCL12 to block its staining of cancer cells." (PMID 35046049, 2022). "The chemokine receptor 4 (CXCR4) and its natural ligand CXCL12 play vital roles in the development of cancer, including cell survival, proliferation, and migration." (PMID 35336029, 2022). "The molecule specifically bound to two targets on the surface of human cancer cells and inhibited CXCL12-induced Jurkat cell migration." (PMID 36284271, 2022). "Certain chemokines, including CCL5 and CXCL12, have further been shown to drive cancer cell metastasis." (PMID 35159113, 2022). "Related to immunotherapy, the PARP inhibitor olaparib, used in the treatment of BRCA mutant cancers has been shown to have a beneficial impact on T‐cell targeting by modulation of SDF1α (CXCL12) production by CAFs." (PMID 35533046, 2022). "TGFβ and CXCL12 pathways, as well as their crosstalk have been considered as the main regulatory mechanisms of cancer cell dynamics." (PMID 36171274, 2022). "Consistent with the finding of increased serum CXCL12 levels, we also observed increased CXCL12 levels in the colonic tissues during the ‘inflammation‐dysplasia‐cancer’ process, especially in miR‐126ΔIEC mice." (PMID 35363937, 2022).
cancer (continued). "Some of these factors were exclusive to CAFs (mainly CXCL10 and CXCL12), others to cancer cells (mainly CXCL7 and CCL20), and some factors, such as CCL2, were common to both cell types." (PMID 35192545, 2022). "Noteworthy, the CXCL12/CXCR4/CXCR7 axis is functionally involved in cancer cell proliferation, survival, and migration." (PMID 36568151, 2022). "CXCL12 was detected in 70% (14/20) PDACs predominantly at the membrane and cytoplasm of cancer cells and in some surrounding monocytes/macrophages stromal cells." (PMID 36359736, 2022). "In conclusion, this study indicates that nCRT elevates the levels of CXCL12 in the plasma membrane of LARC cells and is associated with cancer recurrence." (PMID 34976180, 2022). "Some of the significant cancer hallmark terms are epithelial-mesenchymal transition (MSX1, CXCL12, SCG2, SLIT2), KRAS signaling up (F13A1, ADAMDEC1), inflammatory response (CCL5, VIP), IL-6/JAK/STAT3 signaling (CXCL13)." (PMID 35486660, 2022). "Carcinoma cells themselves occasionally produce CXCL12; more frequently, they foster an environment, including paracrine signaling and cytokines, to stimulate CXCL12 production by stromal cells." (PMID 36244987, 2022). "The chemokine receptor 4 (CXCR4) and 7 (CXCR7) are G-protein-coupled receptors (GPCRs) activated through their shared ligand CXCL12 in multiple human cancers." (PMID 33937018, 2021). "On the other hand, our results show that exposure of cancer cells to relatively high levels of CXCL12 induces the UPR and calreticulin release, which together with CD47 internalization contribute to cell phagocytosis by macrophages." (PMID 34561422, 2021). "In cancer, CXCL12 has been studied in depth in various tumors, and is expressed in cancer cells and most of the cells of the TME, underscoring its role as a main player in metastasis." (PMID 33530455, 2021). "Lidocaine inhibited cancer progression and metastasis via blocking the signaling of chemokine CXCL12 and the activation of its receptor CXCR4." (PMID 34249706, 2021). "Several CXCL12 isoforms have been reported, and their potentially distinct roles in cancer progression remain to be determined." (PMID 33753872, 2021). "At odds with these studies, CXCL12 has also been reported to suppress cancer metastasis by regulating CXCR7 receptor expression." (PMID 33753872, 2021). "CXCL12/CXCR4/CXCR7 axis plays a role in cancer regulating cell migration and proliferation, as well as angiogenesis." (PMID 33937018, 2021). "As a pharmacological compound, EPI-X4 behaves like a typical CXCR4 antagonist and blocks CXCL12 mediated signaling and cancer cell migration in vitro and mobilizes stem cells in vivo." (PMID 33941197, 2021). "CXCL12, also known as stromal cell-derived factor-1, and its localized receptors participate in cellular interaction during cancer progression and metastasis." (PMID 34975909, 2021). "Cancer cell motility can be influenced by the CAF expression of chemotactic chemokines such as stromal derived factor (SDF-1 or CXCL12), and C-C Motif Chemokine Ligand 2 (CCL2)." (PMID 34071280, 2021). "The importance of the CXCL12/CXCR4 axis in cancer has been extensively shown, which translates in a number of approaches to target this axis." (PMID 34503058, 2021). "The validation of these preliminary results in larger cohorts of ACC patients is mandatory, and further experiments must be conducted to better clarify the role of CXCL12 in mediating the anti-cancer effects of RGZ in ACC." (PMID 34834449, 2021). "This is the first study evaluating the expression and role of CXCL12 and its cognate receptors in ACC, along with their association with the anti-cancer activity of RGZ." (PMID 34834449, 2021). "During the study of gene transcription in a panel of human cancer cell lines and primary culture of human fibroblasts, we identified the CXCL12 and FAP genes that showed high and specific transcription in fibroblasts." (PMID 33804861, 2021).
cancer (continued). "Taken together, our data suggested CXCL12’s down-regulation as a novel potential diagnostic biomarker in CRC patients of different races, cancer stages, genders, age groups, and body weights." (PMID 34473751, 2021). "The use of anti-VEGF antibodies in CRC upregulated CXCL12/CXCR4 signaling between cancer cells and Ly6low monocytes, increasing the latter population and thus generating an immunosuppressive environment and increasing the possibility of therapeutic failure." (PMID 33530455, 2021). "Our findings open new perspectives for repurposing RGZ and other thiazolidinedione PPARγ ligands in the treatment of ACC to specifically target the CXCL12/CXCR4 axis in order to counteract cancer progression." (PMID 34834449, 2021). "CXCL12 also plays an important role in cancer progression and metastasis, influencing overall survival in breast, lung, pancreatic, and esophagogastric cancer." (PMID 34768458, 2021). "TAMs produce chemokines, such as CXCL8 and CXCL12, that are able to program cancer cells in a way that they acquire a CSC-like character and that maintain stemness in oral squamous cell carcinoma, HCC, and renal cell carcinoma." (PMID 34965886, 2021). "To see if also chemotaxis can be effectively inhibited, we incubated cancer T lymphoblasts with different concentrations of JM#21 and its truncated analogs and tested for migration towards physiological concentrations of CXCL12." (PMID 34552197, 2021). "When cancer cells pass through organs with high levels of the chemokine SDF-1/CXCL12, they exit circulation and extravasate." (PMID 33922795, 2021). "CAFs have been shown to secrete high levels of SDF-1/CXCL12 in different cancer types including EBV-positive NPCs." (PMID 34680337, 2021). "Here, for the first time, we found that the enhanced survival of cancer cells achieved by TAM was mainly mediated by CXCR4 activation from the increased secretion of CXCL12 from CSF-1 activated TAM." (PMID 34069563, 2021). "The pathways in cancer and Thyroid hormone synthesis signaling pathway and the first two genes of CXCL12 and EIF2A are considered to be biomarkers of important biological function in IS." (PMID 33880887, 2021). "Future studies in metastatic PCa models will help to refine the role of CXCL12 in advanced cancer progression." (PMID 33753872, 2021). "While CAF-S1 stimulates cancer cell migration and initiates an epithelial-to-mesenchymal transition through the CXCL12 and TGF-β pathways, the highly contractile CAF-S4 induces cancer cell invasion in three dimensions via Notch signaling." (PMID 34305902, 2021). "CXCL12 is a chemokine that plays a crucial role in hematopoietic stem cell support and has been extensively reported to be involved in several cancer-related processes." (PMID 33530455, 2021). "CXCL12 and its receptors have been extensively studied in cancer, including their influence on cancer stem cells (CSCs) and their niche." (PMID 33530455, 2021). "Modulators secreted by pCAFs, such as TGF-β, IL-6 and CXCL12, are able to promote the proliferation and invasion of cancer cells." (PMID 34635121, 2021). "ACKR3 is an atypical chemokine-like receptor that binds CXCL12 a ligand with critical roles in angiogenesis, development, inflammation, immune challenges, and cancer." (PMID 34583741, 2021). "HIF-1 induces the secretion of a variety of chemokines responsible for myeloid cell recruitment, such as CCL5 and CXCL12 by cancer cells." (PMID 33407613, 2021). "The CXCL12/CXCR-4 axis is one of the most important pathways involved in cancer growth and metastasis." (PMID 34069563, 2021). "ACKR3, along with CXCR4, with which it shares a ligand, CXCL12, plays an important role in cancer progression." (PMID 33799570, 2021). "The meta-analysis of CXCL12 expression revealed that it can be used as prognostic biomarker for various cancer types." (PMID 34298991, 2021).
cancer (continued). "More specifically, FABP4 was involved in regulation of lipolysis in adipocytes and CXCL12 participated in pathways in cancer and axon guidance." (PMID 34123594, 2021). "Previous studies have shown that CXCR4 is elevated in MTC tissues and CXCL12/CXCR4 signaling promotes cancer cell proliferation and invasion." (PMID 33962657, 2021). "Infiltration of pDCs into cancer tissues is associated with poor prognosis correlating with BC lymph node metastasis, with participation of the CXCR4/CXCL12 chemokine axis or stromal cell-derived factor 1 alpha (SDF-1α)." (PMID 34337083, 2021). "CXCR4 is a chemokine receptor that binds the CXCL12 (also known as SDF-1), which plays a pivotal role in tumorigenesis and cancer metastasis." (PMID 34226507, 2021). "CXCL12 potentiates CXCR7+/CXCR4+ cancer cell trans-endothelial migration toward CCL19 and CXCL13, chemokines expressed by ECs in the lymph nodes." (PMID 33937018, 2021). "The truncated EPI-X4 JM#21 derivatives antagonized cancer cell migration towards CXCL12 even more potently than the precursor peptide." (PMID 34552197, 2021). "Researchers employed chemokine factor motif chemokine ligand 12 (CXCL12) to stimulate cancer cells to express more integrin, and purified cancer cell membranes to carry PLGA NPs." (PMID 33336610, 2021). "SPP1 and CXCL12 are chemokines demonstrated to stimulate angiogenesis both during normal organ development and under pathological conditions, such as various cancers." (PMID 34099632, 2021). "CXCL12 is also one of the chemokines involved in epithelial-mesenchymal transition (EMT) in different types of cancer." (PMID 33407613, 2021). "In this study, we show that CXCL12 from TAMs exerts a paracrine effect on cancer cells via CXCR-4 and protects cancer cells from damage caused by docetaxel." (PMID 34069563, 2021). "Experimental performed in mouse models strongly suggest that EPI-X4 blocks CXCR4/CXCL12 cell signaling, thus suppressing the migration and invasion of cancer cells." (PMID 34208189, 2021). "Accumulating evidence indicates that CXCL12 is pivotal in cancer progression and therapy resistance." (PMID 33753872, 2021). "Recently, the endogenous human peptide EPI-X4 was identified as a natural CXCR4 antagonist that effectively blocks CXCL12-mediated receptor internalization and suppresses the migration and invasion of cancer cells towards a CXCL12 gradient." (PMID 33669329, 2021). "Antimetastatic effects of systemic CXCL12 blockade have been interpreted based on the paradigm that bone marrow MSC attract cancer cells via endocrine CXCL12 signaling." (PMID 33753872, 2021). "Meanwhile, seven common genes, FOSL1, S100A9, CXCL12, ID2, PRS6KA3, AREG, and DUSP6, have been used as the target biomarkers and even the diagnostic tools in cancer therapy." (PMID 34490085, 2021). "Until very recently, CXCR4 was thought to be the only receptor to bind CXCL12; however, CXCR7 has emerged as another receptor for CXCL12, with implications in cancer development." (PMID 33530455, 2021). "The major interest in this chemokine as a potential target for cancer therapy flows from studies that mostly investigated the direct interaction between CXCL12 and CXCR4 on cancer cells." (PMID 34944943, 2021). "For instance, researchers found that cancer-associated fibroblasts (CAFs) in TME induced epithelial-mesenchymal transition (EMT) and cisplatin resistance in OC via CXCL12/CXCR4 axis." (PMID 33763130, 2021). "The CXCR4/CXCL12 axis is known to play an integral role in promoting cancer cell progression via phosphorylation of Akt at Ser473 (pAktSer473) that induces epithelial-to-mesenchymal transition (EMT)." (PMID 34070538, 2021). "CXCL12 is a stromal secreted factor that was essentially involved in regulating the TME among cancers." (PMID 34801033, 2021).
cancer (continued). "The miRNAs participated in the downregulation of CXCL12, which is ubiquitously expressed in the bone marrow and is responsible for chemotactic migration of cancer cells from the primary site toward the bone." (PMID 34831048, 2021). "Secretion of CCL23, -24, -25, -26, CXCL12, and -16 was increased in all spheroid cultures upon monocyte addition in a cancer cell line-dependent fashion but was only marginally secreted by control macrophages." (PMID 34451433, 2021). "Studies have shown that cancer cells in TME can induce overexpression of CXCL12 by autocrine or paracrine, and then activate downstream pathways to affect immune status and promote cancer cell proliferation and distant metastasis." (PMID 33894748, 2021). "Tumors enriched in the carcinoma-associated fibroblasts involved in TME can secrete hepatocyte growth factor (HGF, ligand for c-Met receptor), and C-X-C motif chemokine 12 (CXCL12, THE ligand for chemokine receptor CXCR4)." (PMID 34944829, 2021). "Our study showed CXCL12 expression was extremely low in blood and bone marrow compared with other normal tissues and also downgraded in hematological neoplasms among pan-carcinomas." (PMID 34327063, 2021). "Nowadays, the relevance of the CXCL12/CXCR4 axis in cancers has been ascertained through the impact of the CXCR4 genomic landscape in clinical settings." (PMID 32260318, 2020). "Increasing V1 or LIF and V2 or TGFβ are signs of fibroblast activation and transformation of NAF to CAF, also overexpression of U2 or CXCL12 is sign of cancer promoting role of CAF and invasiveness of cancer cells." (PMID 32384110, 2020). "CXCL11 transcripts were significantly more abundant in cancer‐replaced nodes, while CXCL12 transcripts were significantly more abundant in cancer‐free nodes." (PMID 31755096, 2020). "EPI-X4 blocks CXCL12-mediated signaling, thereby preventing the migration of cancer cells, mobilizing hematopoietic cells and inhibiting inflammatory responses in vitro and in mouse models." (PMID 32994431, 2020). "Potential mechanisms of resistance include down-regulation or internalization of surface CXCR4, heterogeneous expression in cancer cells resulting in incomplete targeting, and potential competition with locally increased CXCL12 concentrations." (PMID 32260318, 2020). "The CXCR4/CXCL12 pathway has substantial literature support that establishes the role of the CXCR4 gene in cancer." (PMID 33092526, 2020). "The chemokine receptors CCR7 and CXCR4, which are expressed by invading cancer cells, bind to secreting chemokines such as CCL21 and CXCL12, to recruit more cancer cells towards lymphatic vessels." (PMID 33172072, 2020). "Both in vitro and in vivo studies suggest that the expression level of CXCL12/CXCR4 in cancer cells is positively correlated with microvessel density." (PMID 33363463, 2020). "While CCL14 and XCL1 have shown only good prognostic value, other chemokines such as CCL5, CCL20/CCR6, CCR7, CXCL1, CXCL8, and CXCL12/CXCR4 have consistently played the role of poor prognostic markers in different kinds of cancer." (PMID 31991604, 2020). "PDA cancer cells exhibit an extracellular complex that include CXCL12, the ligand for CXCR4, which is expressed by cancer associated fibroblasts (CAF)." (PMID 33584695, 2020). "Taken together, these findings illustrate the contribution of CXCL12 axis to cancer chemoresistance." (PMID 33363463, 2020). "CXCL12 expressing organs are a target for CXCR4 positive cancer cells and blocking the CXCL12/CXCR4 interaction using neutralizing antibodies (nAb) significantly inhibits experimental metastases." (PMID 33414786, 2020). "In this setting, the decreased expression of CXCL-12 leads to intra-tumoral T cell accumulation, which in turn synergizes with immuno- or chemotherapy to reduce cancer cells abundance." (PMID 33553157, 2020). "TNFRSF11B stimulates the secretion of CXCL12, which was suggested to contribute to TC development by regulating cancer cell migration and invasion." (PMID 33240576, 2020).